CACNA1C (calcium voltage-gated channel subunit alpha1 C)
Diseases named in the same sentence as CACNA1C in open-access papers (continued):
Sharing a sentence is not in itself a finding about the gene and the disease.
schizophrenia (continued). "Interestingly, none of the reproducible GWAS-associated loci in schizophrenia CACNA1C, CACNA1H, and CACNB2 (Schizophrenia Working Group of the Psychiatric Genomics, 2014) was detected in our dataset." (PMID 28713243, 2017). "For example, the rs1006737 polymorphism in the gene encoding voltage-dependent L-type calcium channel subunit alpha-1C (CACNA1C) was identified in early GWAS of bipolar disorder and schizophrenia, but its biology was unknown." (PMID 29179742, 2017). "Taken all those findings into account, our present data suggest that CACNA1C could potentially impact the biological processes more relevant to cortical surface area and thus contribute to the pathophysiology of schizophrenia." (PMID 27683010, 2016). "Altogether, our findings lend support to the view that CACNA1C might be involved in impaired cognitive functions, especially working memory, in schizophrenia." (PMID 27683010, 2016). "Interestingly, HNRNPH1 binding affinity and splicing can be modulated by genome-wide significant SNPs associated with bipolar disorder, major depressive disorder, and schizophrenia, including rs1006737 (CACNA1C), rs2251219 (PBRM1), and rs1076560 (DRD2)." (PMID 26658939, 2015). "CACNA1C minor alleles have been associated with both bipolar disorder and schizophrenia and nonmotor caudate subregions have been found to be important for integrating cognitive and emotional processing." (PMID 24944871, 2014). "Of interest, the VRK2 region (2p16.1) was identified in the previous sample after including a large schizophrenia replication sample, and the ITIH4 region (3p21.1), ANK3 (10q21) and CACNA1C (12p13.3) were discovered previously in the same, combined schizophrenia and bipolar disorder sample." (PMID 23637625, 2013). "However, since PSI regulatory elements conveying evolution perspectives, they can bring new insights into complex regulation mechanisms as shown in the LRP4 example here and previous examples of SLC2A9 regulating urate levels and CACNA1C regulating Bipolar Disorder and Schizophrenia." (PMID 37056664, 2023). "Furthermore, genes (including GRM1, ADK, CACNA1C, CRK and GAB1) which the most significant SNPs of the five first-generation antipsychotics specific analyses are located within were both associated with the schizophrenia and heart diseases." (PMID 35136033, 2022). "In summary, there is no consensus on whether CACNA1C is associated with schizophrenia or if there are differences in susceptibility to schizophrenia between Asians and Europeans." (PMID 32770953, 2020). "Increased expression of hsa-miR-208b-3p, hsa-miR-494-5p, and hsa-miR-208a-3p may augment susceptibility to schizophrenia by simultaneously conferring susceptibility to apoptosis and altering neural processing and connectivity through the suppression of BCL2 and CACNA1C, respectively." (PMID 32194626, 2020). "Significantly, genetic variants in CACNA1C and CACNA1D (coding for the alpha-1 subunits Cav 1.2 and Cav 1.3 respectively) are some of the most robust genetic risk alleles associated with the development of mental health disorders, including schizophrenia and bipolar disorder." (PMID 31554851, 2019). "Genome-wide association studies (GWAS) of patients with bipolar disorder, schizophrenia and autism spectrum disorders (ASD) have identified gain- and loss-of-function mutations in CACNA1C, the gene encoding the α1C subunit of the voltage-gated L-type calcium channel (LTC) Cav1.2." (PMID 31868578, 2019). "We prioritized 101 schizophrenia genes, including 15 that are targeted by approved or investigational drugs (e.g., DRD2, GRIN2A, CACNA1C, GABBR2)." (PMID 41639063, 2026). "The core genes were identified in Cytoscape software and the results showed that NRXN, CACNA1C and GRIN2A are hub genes in schizophrenia." (PMID 40259965, 2025). "Further studies are needed to investigate the potential pleiotropic role of CACNA1C and KCNH2 variation in the disease architecture of schizophrenia and CADF." (PMID 36421807, 2022).
schizophrenia (continued). "A total of 5 CACNA1C SNPs and 9 KCNH2 SNPs were found and genotyped in 77 unmedicated schizophrenia patients and 144 healthy controls." (PMID 36421807, 2022). "However, the association between the CACNA1C gene and schizophrenia has not been determined." (PMID 32770953, 2020). "RAD51AP1 and AQR are novel interactors of the calcium channel CACNA1C and the nicotinic receptor CHRNA7 respectively in the schizophrenia interactome, found to have an anti-correlated expression in schizophrenia and acetazolamide treatment." (PMID 31481665, 2019). "Therefore, variations at CACNA1C could affect signal transduction and cytoskeleton plasticity and thus lead to aberrant brain structure and function, which may contribute to the etiology of schizophrenia." (PMID 27683010, 2016). "Combined with the genetic results implicating L-type calcium channel genes CACNA1C and CACNB2 in schizophrenia, depression, bipolar disorder, autism, and ADHD, this model further implicates Ca2+ channels in neuropsychiatric illness." (PMID 25762938, 2015). "Moreover, four other schizophrenia associated genes (TCF4, CACNA1C, CSMD1, and C10orf26) identified in that study contain predicted miR-137 binding sites, suggesting that the interplay between miR-137 and its target genes could be involved in the etiology of schizophrenia." (PMID 25250332, 2014). "Also, our PPI network analysis identified NRXN, CACNA1C, and GRIN2A as hub genes in schizophrenia." (PMID 40259965, 2025). "The CACNA1C could in part explain clinical manifestations in our proband, therefore we propose CACN1C as a new candidate gene contributing to epilepsy, ID, and schizophrenia." (PMID 34210021, 2021).
bipolar disorder (107 papers, 2011 to 2026). A disorder of the brain that causes unusual shifts in mood, energy, activity levels and the ability to carry out day-to-day tasks. "A recent study in older adults found that a genetic test used as a screener, namely the presence of the variant RS1006737 of CACNA1C, was found to be strongly linked to Bipolar Disorder." (PMID 40364050, 2025). "SNPs in CACNA1C interact with stress exposure, influencing the risk for depressive symptoms and bipolar disorder." (PMID 40565009, 2025). "The rs10466907 variant of CACNA1C is associated with cognitive recovery after a major depressive episode in bipolar disorder." (PMID 39228919, 2024). "In a human brain study on bipolar disorder, the rs1006737 A allele of the CACNA1C gene was associated with gray matter volume, functional connectivity within the corticolimbic frontotemporal neural system, and mean thickness of cortical brain areas." (PMID 39228919, 2024). "The genetic variant RS1006737 of CACNA1C, found to be associated with bipolar disorder diagnosis, was investigated." (PMID 37916199, 2023). "CACNA1C rs1006737 A allele, identified as a genetic risk variant for bipolar disorder (BD), is associated with anomalous functional connectivity in adults with and without BD." (PMID 36637564, 2023). "Five SNPs were associated with bipolar disorder, namely rs541349080, rs7295590, and rs7979389 of the CACNA1C genotype; rs145322445 of the GRID1 genotype; and rs35648458 of the SIRT1 genotype." (PMID 38012695, 2023). "CACNA1C is also a risk gene for bipolar disorder and circadian rhythm genes have been found to be related to bipolar disorder risk." (PMID 35844244, 2022). "CACNA1C is associated with bipolar disorder, autism spectrum disorder, major depression, and other central nervous system (CNS) disorders." (PMID 32770953, 2020). "The CACNA1C gene polymorphism rs1006737 A allele has been strongly associated with increased risk for bipolar disorder (BD) and with modulation of brain morphology." (PMID 28398341, 2017). "The Psychiatric GWAS Consortium Bipolar Disorder Working Group reported genome-wide, significant association between CACNA1C variant rs4765913 and bipolar disorder." (PMID 28792954, 2017). "The CACNA1C gene, encoding a subunit of the L-type voltage-gated calcium channel is one of the best-supported susceptibility genes for bipolar disorder (BD)." (PMID 27271857, 2016). "First, genomic data show that LTCC genes, especially CACNA1C, which encodes the Cav1.2 alpha subunit, are part of the aetiology of bipolar disorder and several related phenotypes." (PMID 27240535, 2016). "A previous meta-analysis of genome-wide association study (GWAS) identified that single nucleotide polymorphism (SNP) rs1006737 in CACNA1C was significantly associated with bipolar disorder (p = 7.0×10−8)." (PMID 26204268, 2015). "In genome-wide association studies and exome sequencing studies, CACNA1C has emerged as a new candidate gene for neuropsychiatric disease, including bipolar disorder, major depression, schizophrenia, and autism." (PMID 25620733, 2015). "CACNA1C encodes the α subunit of the L-type voltage-gated calcium channel and is a strong candidate for both bipolar disorder and general psychiatric morbidity." (PMID 24489884, 2014). "Genetic markers in the genes encoding ankyrin 3 (ANK3) and the α-calcium channel subunit (CACNA1C) are associated with bipolar disorder (BP)." (PMID 24716743, 2014). "CACNA1C is a well-established susceptibility gene for bipolar disorder, SCZ, and major depressive disorder." (PMID 24901509, 2014). "CACNA1C was recently implicated as one of the most significant genes in a mega-analysis of genome-wide association studies (GWAS) of bipolar disorder carried out by the Psychiatric GWAS Consortium (PGC)." (PMID 23358228, 2013).
bipolar disorder (continued). "Two examples of particular interest to us were CACNA1C (voltage-dependent L-type calcium channel subunit alpha-1C), which is one of the few bipolar disorder gene candidates, and MLL2, which is implicated in leukemia and encodes a histone methyltransferase." (PMID 21958622, 2011). "In addition, we used CRISPR to develop isogenic cell lines from the same bipolar disorder patients in which the G to A polymorphism in CACNA1C has been repaired." (PMID 39056776, 2024). "The CACNA1C gene (especially the rs1006737 A allele) is robustly associated with bipolar disorder and might be crucial in molecular biological research on the set of interacting proteins involved in the calcium channel activity in bipolar disorder." (PMID 39228919, 2024). "Furthermore, the rs7297582 T allele of CACNA1C is associated with a risk of bipolar disorder and poor cognitive performance." (PMID 39228919, 2024). "CACNA1C, especially rs1006737 and rs7297582, may be strongly associated with the onset of bipolar disorder, cognitive decline in bipolar disorder, and dementia." (PMID 39228919, 2024). "The CACNA1C gene may not only be associated with the onset of bipolar disorder but also potentially affects the course of cognitive function and brain imaging." (PMID 39228919, 2024). "Moreover, a cross-sectional study of young adults found a gene × environment interaction in the association of CACNA1C polymorphisms with bipolar disorder, with variant carriers exposed to childhood trauma at greater risk." (PMID 37845746, 2023). "CACNA1C methylation has been implicated in bipolar disorder and suicide attempts patients." (PMID 34282125, 2021). "This is opposite of most findings suggesting reductions in specific aspects of cognitive and emotional processing, but congruent with a recent study suggesting that CACNA1C minor allele carriers with bipolar disorder may have improved working memory." (PMID 24944871, 2014). "Furthermore, tau phosphorylation is known to increase in the cerebrospinal fluid (CSF) in patients with Alzheimer’s disease, and the rs1006737 variant of CACNA1C is significantly associated with hyperphosphorylated tau/total tau ratio in the CSF of patients with bipolar disorder." (PMID 39228919, 2024). "For instance, CACNA1C is an important gene in the transportation of calcium ions and is associated with the increasing risk of arrhythmia, and the A allele of the single nucleotide polymorphism (SNP) rs1006737 in CACNA1C was correlated to a higher risk of bipolar disorder." (PMID 37161899, 2023). "In addition, trials using LTCC antagonists in bipolar disorder can (and should) now select or stratify participants based on CACNA1C risk genotype, as this may modify the treatment effect, and in due course may allow pharmacogenetic prediction of response." (PMID 27240535, 2016). "Analysis of medical comorbidity phenotypes in the Mayo Clinic Bipolar Disorder Biobank precluded the replication of the associations between CACNA1C and cardiac dysrhythmias and between C11orf80 and headache including migraine, as these phenotypes were not assessed in the biobank cohort." (PMID 27529678, 2016). "CACNA1C and GRID1 are common SNP genotypes for depressive disorder and bipolar disorder and should be considered associated with affective psychosis." (PMID 38012695, 2023). "Among the 5 genotypes associated with affective psychosis, CACNA1C and GRID1 were identified as common genes for bipolar disorder and depressive disorder, and CACNA1 was identified as the genotype most highly associated with affective psychosis." (PMID 38012695, 2023). "A total of 5 SNPs belonging to the CACNA1C, GRID1, and SIRT1 genotypes were significantly correlated with bipolar disorder (P < .001), with the majority belonging to the CACNA1C." (PMID 38012695, 2023).
bipolar disorder (continued). "Accordingly, CACNA1C and GRID1 were identified as common genes associated with both bipolar disorder and depressive disorder, suggesting that different types of psychosis not only have their own associated genes but also have common genes." (PMID 38012695, 2023). "Five SNPs were identified as associated with bipolar disorder and belonged to the CACNA1C, GRID1, and SIRT1 genotypes, with the majority belonging to the CACNA1C genotype." (PMID 38012695, 2023). "The first genome-wide significant association between an LTCC gene and a psychiatric disorder was for CACNA1C and bipolar disorder." (PMID 36154842, 2022). "Genome-wide association studies have identified that CACNA1C and CACNB3, which encodes the VGCC β subunit, are involved in the development of bipolar disorder." (PMID 26136667, 2015). "In 2002, a family-based association study revealed for the first time that CACNA1C, which encodes the VGCC pore-forming α1 subunit, is associated with bipolar disorder." (PMID 26136667, 2015). "Previous GWA studies of bipolar disorder have implicated several potential susceptibility genes, such as SYNE1 on chromosome 6q25.2, ODZ4 on 11q14.1, ANK3 on 10q21.2, CACNA1C on 12p13.3, and NCAN on 19p13.1." (PMID 23326512, 2013). "Using the FDR method in bipolar disorder alone, an additional locus was identified, close to CACNA1C (12p13.3)." (PMID 23637625, 2013). "Subsequently CACNA1C and ZNF804A were proposed as common risk variants for both bipolar disorder and schizophrenia and a Meta-analysis additionally added the MHC-locus as a common risk factor for both diseases." (PMID 21702894, 2011). "For bipolar disorder the most promising results have been reported for CACNA1C and ANK3 (ankyrin 3, node of Ranvier)." (PMID 21702894, 2011). "In conclusion, the genes CACNA1C, GABBR2, SCN2A, CTSH, MSRA, and SH3PXD2A may be associated with the neuro-progression of bipolar disorder to dementia." (PMID 39228919, 2024). "In conclusion, CACNA1C, GABBR2, SCN2A, CTSH, MSRA, and SH3PXD2A may be associated with the neuro-progression of bipolar disorder to dementia." (PMID 39228919, 2024). "CACNA1C SNPs have been repeatedly detected in studies on bipolar affective disorder (BAD)." (PMID 38328521, 2023). "These genes are highly associated with various mental disorder phenotypes, such as neurodevelopmental disorders, intellectual disability, bipolar disorder, anxiety, and depression, and there is increasing evidence that CACNA1C expression in the brain directly regulates depression-related behaviors." (PMID 36011346, 2022). "Therefore, we aimed to investigate the impacts of six CACNA1C SNPs on cognitive recovery in a six-week open label trial for bipolar depression." (PMID 28765577, 2017). "In this six-week open-label trial for treating bipolar depression, we found preliminary evidence that CACNA1C SNP rs10466907 may have impacts on cognitive recovery." (PMID 28765577, 2017). "CACNA1C genotype may also influence other domains relevant to bipolar disorder and its therapy, including resilience, depressive symptoms and reward responsiveness, but these require further investigation." (PMID 27240535, 2016). "According to GWAS, the CACNA1C, GABBR2, SCN2A, CTSH, MSRA, and SH3PXD2A genes were common between bipolar disorder and dementia." (PMID 39228919, 2024). "The results showed that the genes CACNA1C, GABBR2, SCN2A, CTSH, MSRA, and SH3PXD2A were overlapping between patients with bipolar disorder and dementia." (PMID 39228919, 2024). "Accordingly, the CACNA1C, GRID1, and SIRT1 genotypes were identified as carrying the highest risks of bipolar disorder." (PMID 38012695, 2023). "Accordingly, CACNA1C and GRID1 were identified as common genotypes for bipolar disorder and depressive disorder." (PMID 38012695, 2023). "Associations between LTCC genes and psychiatric illness are not limited to CACNA1C, nor to bipolar disorder." (PMID 27240535, 2016).